ELN (elastin)
Diseases named in the same sentence as ELN in open-access papers (continued):
Sharing a sentence is not in itself a finding about the gene and the disease.
aneurysm (continued). "Multifunctional nanoparticles are an innovative approach that simultaneously targets both elastin degradation and SMC dysfunction, providing a comprehensive strategy for aneurysm treatment." (PMID 39595942, 2024). "The degradation of elastin in aneurysms is primarily mediated by the upregulation of MMPs, particularly MMP-2 and MMP-9, which break down the ECM components, including elastin and collagen." (PMID 39595942, 2024). "Elevated expression of miR-29a/b has already been shown to negatively affect key genes involved in vascular ECM structure and turnover, such as collagens (COLLs), elastin (ELN), and ECM-modifying enzymes, contributing to aortic damage and aneurysm development." (PMID 39767655, 2024). "Compared with normal aortic walls, the features of an aneurysm, such as inflammatory cell involvement and ECM degradation, especially elastin degradation, can be utilized as potential targets." (PMID 37080941, 2023). "Notably, the losses of media elastin were comparable between the 2 groups, with a complete loss at the anterior and residual elastin at the posterior of the aortic wall, suggesting that the differences in aneurysms were not the consequence of the surgical variation." (PMID 36625347, 2023). "Therefore, it may be conjectured that a significant decrease in rupture pressure values with age exclusively among CAs in the aneurysm group indicates more pronounced progression of elastin degradation and collagen stiffening within the arterial wall compared to CAs in the non-aneurysm group." (PMID 35717502, 2022). "Elastin and collagen are the main ECM proteins involved in pathological remodeling of the aortic wall upon aneurysm formation." (PMID 35492343, 2022). "More recently, VSMC-specific elastin deficiency was shown to result in almost a complete depletion of elastic lamina in the arterial wall, lengthening and thickening of the ascending aorta, mild luminal obstruction, aortic coarctation, and secondary cardiomyopathy, but not dilation or aneurysm." (PMID 33514025, 2021). "Collagen and elastin are the most important ECM proteins which are responsible for maintaining the tensile strength of blood vessels and preventing aortic dilation and aneurysm rupture." (PMID 34970414, 2021). "Here, we successfully demonstrate that such targeted delivery of pentagalloyl glucose (PGG) restores degraded elastin, reduces MMP activity and infiltration of inflammatory cells, and regresses already developed aneurysms in elastase-induced AAA model." (PMID 32218565, 2020). "Hence, we can postulate that elastin disruption within the adventitia and innermost media of the aortic wall along with its inability to regulate tissue development and elasticity may be the key in distinguishing the onset of ascending aneurysm formation." (PMID 31679706, 2020). "Considering the process of aneurysm formation in general, aortic media remodelling is characterised by altered extracellular matrix (ECM) proteins (e.g., collagen, elastin, fibrillin) production and deposition." (PMID 29671812, 2018). "Although MMP2 also plays a significant role in elastin degradation within aneurysms, tRF-AspGTC does not appear to be involved in the pathways regulating MMP2 expression and activation." (PMID 39776588, 2025). "Conversely, treatment with heat-killed A. muciniphila and A. muciniphila secretions did not impact aneurysm diameter, elastin degradation, or circulating endotoxin levels in AAA mice, despite demonstrating improvements in intestinal permeability." (PMID 40299521, 2025). "Multiple injections of MUSE cells most effectively prevented aneurysm growth and increased medial elastin compared to non-MUSE (SSEA-3−) cells and normal Bm-MSCs." (PMID 38895536, 2024). "A screening study revealed that patients with a ruptured AAA greater than 6 cm display increased levels of elastin-derived peptide, compared to those with small aneurysms that have not ruptured." (PMID 37799778, 2023).
aneurysm (continued). "Areas of unstructured elastin deposition were found in the post-EVAS specimens and could be a reflection of a biological interaction between EVAS and the aneurysm wall." (PMID 37192857, 2023). "Additionally, studies on biochemical markers have demonstrated a positive relationship between serum elastin peptides (SEP) and aortic distensibility, as well as between SEP and aneurysm growth." (PMID 37410199, 2023). "Similar to what is observed in the long-term Ang II model, massive wall expansion, media thickening, and elastin breakdown were evident but with no sign of lipid accumulation or atherosclerosis in the aneurysm sites from the CCN2SMCΔ group." (PMID 36625347, 2023). "For example, if there are pollutants in the elastin used in the elastase-induced model, the aneurysm will not be induced." (PMID 36737432, 2023). "Finally, it is clear that inflammation is a key component in this model as aneurysm growth correlates with inflammatory infiltrate, especially in acute stages of AAA development after considerable elastin damage." (PMID 34997075, 2022). "Among these, miRNA-29b was found to play pivotal role in the formation of aneurysms, post-transcriptionally regulating the expression levels of multiple targets with a function in the ECM collagens, elastin, and fibrillin and modulating the aortic SMCs’ synthetic phenotype switch." (PMID 35892496, 2022). "Previous investigations have characterized this method of AAA progression: elastin content has been found to be lower in aneurysms compared to healthy tissue, and ruptured AAAs found to have an even lower elastin content than non-ruptured ones." (PMID 33659281, 2021). "Elastin Van Gieson (EVG) staining confirmed the appearance of elastin damage in mice treated with AngII, regardless of genotype or aneurysm incidence." (PMID 32617140, 2020). "LOX knockout mice are prone to thoracic aortic aneurysm and dissection and die soon after birth, with a 60% reduction in elastin crosslinks observed in aortic tissue, underscoring LOX inactivation as a key prognostic indicator for aneurysm and dissection prognosis." (PMID 31214600, 2019). "This aneurysm showed more infiltration of macrophages and neovascularization in the aortic wall, more upregulation of MMP2 and MMP9 expression in the media, but less elastin content, endothelial recovery and a lower SMC content." (PMID 23844207, 2013). "Accelerated inflammatory processes during aneurysm development lead to increased levels of matrix metalloproteinases (MMPs) and destabilization of the vessel wall through the degradation of the structural components of the extracellular matrix (ECM), mainly collagen and elastin." (PMID 38928311, 2024). "FSI was not employed, considering the small amplitude of the AAA wall motion within the cardiac cycle which was measured to be 1.4% of the aneurysm diameter in a cohort of 56 patients, as a result of the reduction in the aorta compliance along its length and the lack of elastin because of aging." (PMID 38391630, 2024). "Verhoeff's Van Gieson stain (stains for elastin) of specimens showed that the aneurysm dome wall lacked elastin in both groups 1 and 2, however, compared with group 2, elastin at the aneurysm neck in group 1 was digested more sufficiently." (PMID 35860490, 2022). "In aneurysm cross sections, elastin content was insignificantly higher in the cycloastragenol group (10.5% ± 5.9% vs. 19.9% ± 16.8%, p = 0.20), with more preserved elastin lamellae structures (p = 0.0003) and without microcalcifications." (PMID 35203568, 2022). "However, a loss of VSMC-elastic fibers connections does not appear to be sufficient to cause aneurysmal disease, given that elastin deficiency associates with obstructive arterial diseases and VSMC over-proliferation, but not aneurysm." (PMID 33514025, 2021).
aneurysm (continued). "We tested the hypothesis that nanoparticle (NP) therapy that targets degraded elastin and delivers anti-inflammatory, anti-oxidative, and ECM stabilizing agent, pentagalloyl glucose (PGG) will reverse advance stage aneurysm in an elastase-induced mouse model of AAA." (PMID 32218565, 2020). "No such histoarchitectural features of aneurysm were observed in the aortae of myeloid-Notch1+/-;Apoe-/- mice infused with AngII which displayed a well-defined lumen, no visible elastin fragmentation and minimal inflammatory cell infiltration." (PMID 28562688, 2017). "However, the SMC, elastin and type III collagen content decreased significantly in Group C, indicating that periaortic CaCl2 incubation might promote aneurysm formation and progression when combined with elastase incubation." (PMID 23844207, 2013). "MMPs can degrade elastin, the major component of ECM, and the degradation products are capable of inducing inflammatory cell infiltration, which in turn increases MMP synthesis through a positive feedback loop and changes aortic wall elasticity, resulting in aortic expansion and aneurysm formation." (PMID 25984324, 2013). "Moreover, simple elastin may not induce successful aneurysms due to the presence of pollutants in the preparation." (PMID 36737432, 2023). "However, the elastin grade was not different among the aneurysm, eSHE1 and eSHE0.5 groups." (PMID 34285224, 2021). "Characteristic vessel wall remodeling in aneurysms was demonstrated by EVG staining, and continuous and wavy elastic lamellae could be found in saline-treated Apoe−/− and Apoe−/− IKKε−/− mice, as well as degradation of elastin filaments in both in Ang II-treated mice." (PMID 32064021, 2020). "Furthermore, an intragroup analysis of AAA surgical specimens collected from various regions of the aneurysm wall revealed a significant negative correlation (r = -0.85; P = 0.006) between DAB staining intensity of CCR2 and VVG-stained elastin fiber content." (PMID 40365294, 2025). "In our study, nicotine treatment reduced aneurysmal MMP9 activity, although there was no obvious effect on elastin integrity, nor were there any differences in MMP9-positive cells in the aneurysm wall, even though nicotine treatment led to the development of larger AAAs." (PMID 37239088, 2023).
emphysema (142 papers, 2004 to 2026). "Its overexpression causes the breakdown of lung tissue structure, especially elastin degradation, which is directly related to the development of emphysema." (PMID 40421300, 2025). "This imbalance between proteases and their physiologic inhibitors “favors” active proteases to degrade lung structural proteins, particularly elastin, leading to the loss of organ architecture, hence emphysema development." (PMID 41007683, 2025). "Other factors implicated in the pathophysiology of emphysema include genetic deficiencies that affect elastin crosslinking, which have drawn particular attention." (PMID 40422205, 2025). "This enzyme was shown to increase the susceptibility of elastin to degradation in vitro, and treatment of LPS-induced pulmonary emphysema with PAD decreased lung elastance and exacerbated airspace enlargement." (PMID 41303415, 2025). "Patients with this disorder are at a higher risk for developing pulmonary emphysema due to the fragility of lung elastin and resultant increased susceptibility to destruction." (PMID 40422205, 2025). "These proteases specifically target elastin, and the loss of elastin leads to the collapse of small airways, ultimately causing emphysema." (PMID 40565035, 2025). "The degradation of elastin leads to loss of lung elasticity and contributes to the development of emphysema, a common feature of COPD." (PMID 38399533, 2024). "Progressive elastin degradation compromises alveolar integrity resulting in the development of emphysema and, when this is associated with airflow limitation, COPD." (PMID 39040588, 2024). "In cases of a copper deficiency, elastin cross-linking becomes impaired, weakening the connective tissue and potentially leading to structural changes in the lungs associated with emphysema-like damage." (PMID 39683514, 2024). "So we suggested that aging is characterized by high levels of protease activity leading to degradation of elastin followed by loss of elasticity of the lung and the development of emphysema." (PMID 39705219, 2024). "Tamoxifen-induced mesenchymal Gαq/11 gene deletion in adult mice resulted in emphysema associated with reduced TGFβ2 and elastin deposition." (PMID 37102682, 2023). "Alpha anti trypsin 1 deficiency is also associated with development of severe emphysema, lung volume loss correlated to serum desmosine/isodesomine content demonstrating elastin degradation is directly linked to disease progression." (PMID 37001705, 2023). "Increases in IFNγ- and IL-6-producing blood T cells to elastin fragments had a positive association with the annual rate of emphysema progression in active smokers." (PMID 34271910, 2021). "α1-Antitrypsin is a neutrophil elastase inhibitor, and its deficiency is associated with a poorly-controlled release of elastase, resulting in the destruction of elastin in the lung tissue, a process mainly associated with the development of emphysema." (PMID 34950055, 2021). "Despite the significance of elastin degradation as a primary cause of loss of lung elasticity and function, it has received little attention as a potential target for the treatment of emphysema." (PMID 34537081, 2021). "The pathogenesis is attributable to emphysema caused by the decomposition of elastin, which constitutes the alveoli, by MMP-12." (PMID 34703996, 2021). "MMP-1, which degrades collagen, and MMP-12, which degrades elastin, have both been strongly implicated in the development of smoke-induced emphysema, at least in animal models." (PMID 30789935, 2019). "It is believed that changes in major lung ECM components, such as collagen subtypes I and III, and elastin, are involved in the loss of elasticity, during emphysema progression." (PMID 30979017, 2019). "As an indirect measure of elastin degradation, skin elasticity reveals a stronger and more convincing association with emphysema than wrinkling and thus represents a viable alternative biomarker." (PMID 31234847, 2019).
emphysema (continued). "Mediators of inflammatory extracellular matrix degradation, elastin loss and chronic inflammation are recognized in the pathogenesis of emphysema and COPD, as well as aortic dilatation, stiffening and aneurysm formation." (PMID 29793484, 2018). "Emphysema is caused by an elastase/anti-elastase imbalance leading to accelerated elastin degradation." (PMID 29558926, 2018). "The association between fragments of elastin, as degraded by neutrophil elastase, and emphysema is particularly interesting as they point to potential targets of pathological tissue remodeling in certain phenotypes of COPD which have not been described before." (PMID 28103932, 2017). "The role of elastin in the alveoli is described in the literature, and results indicate that particularly elastin is a major target in the pathogenesis of emphysema, which supports the finding of emphysema associated with EL-NE." (PMID 28103932, 2017). "Assessing emphysema-causing protease secretion and elastin degradation, we found that OA-NO2 treatment markedly reduced secreted Cat S levels and activity in culture medium." (PMID 27119365, 2016). "RARγ has been associated with elastin production, and its reduced expression appears to be associated with the development of emphysema." (PMID 26462767, 2015). "CHST3 siRNA diminishes accumulation of excessive macrophages and the mediators, leading to accelerate the functional recovery from airway damage by repair of the elastin network associated with pulmonary emphysema." (PMID 26646821, 2015). "Elastin deficiency also causes vascular disease, bronchiectasis, and emphysema in cutis laxa, a more severe defect of elastogenesis." (PMID 22998683, 2012). "Abnormal senescence of mesenchymal precursors in emphysema leads to parenchyma loss, defective production of extracellular matrix proteins, such as elastin and fibronectin, and progressive weakening of the alveolar structures." (PMID 22567106, 2012). "The mechanisms of emphysema induction by intratracheal administration of elastase encompass an initial loss of collagen and elastin." (PMID 15522115, 2004). "One of the critical convergence points in the pathogenesis of pulmonary emphysema may be the release of elastin peptides, which are both a consequence and a cause of elastin degradation due to their proinflammatory properties." (PMID 40422205, 2025). "In line with that, higher vitamin K intake or levels have been linked to lower mortality rates, better lung function, reduced elastin degradation, and decreased risk of emphysema, as indicated by blood levels of biomarkers responsible for crosslinking elastin fibers (desmosine and isodesmosine)." (PMID 40218907, 2025). "Arterial stiffness is likely caused by an imbalance in matrix metalloproteases and is associated with elastin degradation, which leads to elastin destruction in the vasculature and pulmonary emphysema, and it has been suggested that it plays a role as a predictor of cardiovascular events." (PMID 41517298, 2025). "Emphysema is caused by loss of function mutation, which means there is an imbalance between neutrophil elastase in the lung, which destroys elastin, and the elastase inhibitor AAT, which is synthesized in hepatocytes and protects against proteolytic degradation of elastin." (PMID 38633947, 2024). "While the initial repair process mainly consists of elastin degradation and resynthesis, continued alveolar wall injury may be associated with increased collagen deposition, resulting in a mixed pattern of emphysema and interstitial fibrosis." (PMID 39408941, 2024). "In the respiratory system, WBS subjects with ELN haploinsufficiency may be predisposed to the early development of pulmonary emphysema, the elastin in fact, is a key component of elastic fibers within the lung." (PMID 36290706, 2022). "The elastase model we used caused very mild emphysema with elastin breaks in the alveoli." (PMID 34537081, 2021).